NBPF9 (NBPF member 9)
Synonyms: AE01
Tractability: PROTAC: ubiquitination databases record sites on it.
Gene: Protein-coding gene on chromosome 1 (149,052,186 to 149,103,591, reverse strand). Ensembl gene ENSG00000269713.
Subcellular location: Cytoplasm
Subcellular location (Human Protein Atlas): Cytosol; Cytokinetic bridge; End piece; Golgi apparatus; Microtubules; Mid piece; Principal piece; Vesicles
Gene Ontology:
Cellular component: cytoplasm
Genetic constraint (gnomAD): Loss-of-function variants: 39 observed, 33.3 expected, observed/expected ratio (o/e) 1.17, 90% interval 0.91 to 1.53. The synonymous counts are far from expectation, so gnomAD's model fits this gene poorly and the ratio says little. Missense variants: 608 observed, 452.8 expected, observed/expected ratio (o/e) 1.34, 90% interval 1.26 to 1.44. Synonymous variants: 211 observed, 166.52 expected, observed/expected ratio (o/e) 1.27, 90% interval 1.13 to 1.42.
Homologues: Paralogues in human: NBPF14 (98% identical), NBPF10 (97% identical), NBPF26 (82% identical), NBPF8 (82% identical), NBPF12 (81% identical), NBPF20 (74% identical), NBPF1 (74% identical), NBPF19 (74% identical), NBPF11 (70% identical), NBPF15 (56% identical), NBPF3 (42% identical), NBPF4 (26% identical), and 1 more.
Diseases named in the same sentence as NBPF9 in open-access papers:
NBPF9 is named in the same sentence as 6 diseases in open-access papers, as found by Europe PMC text mining. Sharing a sentence is not in itself a finding about the gene and the disease. The quoted sentences say what the papers report.
congenital hypopituitarism (1 paper, 2020). "The NBPF9 gene may be involved in congenital hypopituitarism." (PMID 32733554, 2020).
ovarian carcinoma (1 paper, 2025). A malignant neoplasm originating from the surface ovarian epithelium. "Using independent ovarian cancer cohort (TCGA-OV) we also confirmed high frequencies of mutational alterations in the NBPF gene family including NBPF1, NBPF9, NBPF10, NBPF12 and NBPF14 (> 50%)." (PMID 41316472, 2025).
cancer (3 papers, 2020 to 2025). A tumor composed of atypical neoplastic, often pleomorphic cells that invade other tissues. "Interestingly, MTMR4 and NBPF9 currently have no clear role in cancer or response to radiation." (PMID 37771787, 2023).
NBPF9 also shares sentences with these, for which no sentence is quoted: hypopituitarism (1 paper); pituitary stalk interruption syndrome (1); tumor (1).